EGFR (epidermal growth factor receptor)
Diseases named in the same sentence as EGFR in open-access papers (continued):
Sharing a sentence is not in itself a finding about the gene and the disease.
cancer (continued). "Indeed, EGFR activation by β1-integrin appears critical for cancer invasion and metastasis through the β1-integrin/EGFR/VEGF-A/VEGFR1 signaling axis in which Rab25 plays a bridging role between EGFR phosphorylation and VEGFR1 activation." (PMID 36010606, 2022). "Some cancers especially NSCLC are addicted to the hyperactive EGFR pathway." (PMID 35062949, 2022). "EGFR is also useful as a target of drugs for the development of cancer therapies." (PMID 35884464, 2022). "Furthermore, an ACNPs therapy based on cetuximab, an anti-EGFR conjugated with an NP encapsulating the topoisomerase inhibitor camptothecin, showed a reduction in cancer growth in PC cell lines." (PMID 36106025, 2022). "Therefore, it is of great significance to identify EGFR palmitoylase and depalmitoylase and clarify the regulatory mechanism of EGFR palmitoylation in different cancer types and different mutant environments for personalized treatment of cancer patients." (PMID 35637973, 2022). "EGFR is a transmembrane receptor tyrosine kinase, and the activation or phosphorylation of this region is of great significance for the signaling of proliferation and growth of cancer cells." (PMID 35081265, 2022). "From a further analysis of Kyoto Encyclopedia of Genes and Genomes (KEGG) pathways, we found that the most enriched pathways, such as MAPK, pathways in cancer, adhesion, and EGFR tyrosine kinase inhibitor resistance pathways, affected cell migration and proliferation." (PMID 36362025, 2022). "EGFR expression was high in various human cancers derived from epithelial cells, indicating that EGFR ligands might be used as cancer treatment targets." (PMID 36364116, 2022). "Currently, an increasing number of targeted therapies, including ALK, CDK and EGFR inhibitors combined with conventional radiotherapy and chemotherapy regimens are acknowledged as significant cancer treatment methods for individual therapy and to combat drug resistance." (PMID 35264157, 2022). "The genetically engineered VV, Pexa-Vec (JX-594), targets cancer cells via multiple mechanisms, whereby virus replication is activated by EGFR/KRAS pathway signaling, cellular thymidine kinase (TK) levels, and resistance to type I interferons (IFNs) in cancer cells." (PMID 36221123, 2022). "EGFR is an attractive therapeutic and diagnostic target, and many small molecule inhibitors and antibodies are already FDA approved or undergoing active clinical trials in a number of cancers." (PMID 35053365, 2022). "Cancer associated fibroblasts (CAFs) of ATLL play an important role for CD4 T-cell proliferation via FGF7-FGF1 and PDGFA-PDGFRA/B signaling, and CAFs, particularly EGR-enriched, are also associated with CD8 and NKT expansion by EGFR." (PMID 35464471, 2022). "The situations in these explanations presumably result in the presence of few or no cancer cells in sediment, thus yielding false-negative results for EGFR mutations." (PMID 35141163, 2022). "Furthermore, several light microscopy studies have suggested interactions of EGFR with other ERBB receptors in human cancer cells." (PMID 35612280, 2022). "HPV early genes may act as the stimulating factor to enhance EGFR nuclear trafficking, and nuclear EGFR translocation modulates DNA repair following cisplatin administration, further resulting in cancer cell apoptosis." (PMID 36358752, 2022). "Cancer patients treated with EGFR inhibitors often develop resistance to treatment." (PMID 36407100, 2022). "Reversing EMT by canertinib may further contribute to sensitivity to anti-cancer effects, in addition to EGFR/HER2 inhibition." (PMID 36081848, 2022). "Moreover, clinic-genomic data revealed that HSP27 was more strongly involved in cancer prognosis than EGFR or AKT alone, and that overexpression of HSP27 potentiated negative effects in NSCLC patients." (PMID 35931945, 2022).
cancer (continued). "However, considering that CaCCinh-A01 and DES are non-selective CaCC inhibitors, it cannot be concluded that the reduced EGFR signalling and anti-cancer effects are due to reduced ANO1 current activity." (PMID 36497413, 2022). "Furthermore, CBD and CBG significantly induced cell apoptosis in the EGFR-positive cancer A431 line." (PMID 36568260, 2022). "Therefore, several therapeutic strategies to target the EGFR pathway demonstrated various efficiencies that overcome drug resistance and cancer development." (PMID 35402265, 2022). "These anti-EGFR doxorubicin-loaded immunoliposomes (anti-EGFR ILs-dox) displayed highly efficient binding and internalization in a panel of EGFR or EGFRvIII overexpressing cancer cell lines, as indicated by fluorescence microscopy and fluorescence-activated cell sorter." (PMID 34998092, 2022). "However, these compounds need to be further evaluated for their binding affinity to EGFR-TK and growth inhibition effects on EGFR-positive cancers." (PMID 36568260, 2022). "To gain further pathway and functional insight into possible genetic interactions underlying ARID1A deficiency-driven resistance to anti-EGFR therapy, we next searched for oncogenic dependencies or mutual exclusivities between ARID1A mutations and other alterations in cancer." (PMID 36117191, 2022). "Thus, activation of PPARγ represents a promising approach to ameliorate cutaneous toxicity in patients with cancer who receive anti-EGFR therapy." (PMID 35324426, 2022). "Finally, growth factor receptor bound 7 (GRB7), a multidomain adaptor protein that was previously shown to interact with the H. pylori CagA effector protein, is a critical mediator of EGFR/ErbB signaling involved in cancer development." (PMID 37193047, 2022). "Further studies confirm the crosstalk between EPHA2 and EGFR signaling in cancer." (PMID 36297233, 2022). "Moreover, pathways intrinsic and extrinsic stresses, including iatrogenic stress, trigger robust EGFR trafficking and signaling to provide cancer cells with a survival benefit and resistance to therapeutics." (PMID 37192859, 2022). "We suggest that ND-Cet enhances the uptake ability through the binding of EGFR in cancer cells." (PMID 36678740, 2022). "Taken together, EGFR is extensively involved in cancer progression through a variety of mechanisms." (PMID 36054194, 2022). "An EGFR-mut cancer cell with its concomitant co-adaptations may find itself greatly disadvantaged within the tumor microenvironment of a KRAS-mut cancer and vice-versa." (PMID 35061724, 2022). "One of the aims of this study was to find phenotypic commonalities among EGFR WT cancer patient subgroup unions that might be helpful in selecting responders for immuno-targeted combination therapies." (PMID 36230688, 2022). "Previous randomized clinical trials have shown that addition of EGFR-targeting drugs could significantly improve the marginal benefit for cancer treatment." (PMID 35745775, 2022). "Expression of PD-L1 links with inhibition of EGFR/ERK1/2 signaling cascades in cancer cells." (PMID 35705962, 2022). "EGFR overexpression is a well-known characteristic feature of some cancers." (PMID 36499115, 2022). "The effect of sorafenib, bevacizumab, panitumumab, ramucirumab, sorafenib- bevacizumab, sorafenib-panitumumab and sorafenib-ramucirumab on the protein expression of cleaved CASPASE3, VEGFR2 and EGFR in HepG2 cancer cells was determined by western blot using GAPDH as a normalizer." (PMID 36284117, 2022).
cancer (continued). "Based on these data, we tested whether the EGFR/HER2 downstream signaling pathways collaborated with TAZ to induce cancer in adult livers." (PMID 35439973, 2022). "The activation of EGFR induced by cisplatin has been observed in a variety of cancers, and the extent of its activation may affect the sensitivity of cancer cells to chemotherapy." (PMID 36230734, 2022). "Angiogenesis and cancer cell growth depend greatly on the epidermal growth factor receptor (EGFR)." (PMID 36144596, 2022). "EGFR–SRC–STAT3 signaling plays a vital role in some human cancers." (PMID 35600368, 2022). "Thus, we postulated several molecular candidates, including AKT and STAT3, which contribute not only to cancer cell proliferation but also to the emergence of EGFR TKI resistance." (PMID 35408753, 2022). "Elevated levels of EGFR expression and its ligands have been recognized in several cancers." (PMID 35455447, 2022). "In several cancer types, EGFR expression levels correlate with the disease prognosis." (PMID 36185288, 2022). "Despite the critical role of claudin proteins in regulating the invasive and CSC-like properties of cancer cells, the effects and mechanisms of claudin proteins in the regulation of EGFR-TKI resistance are unknown." (PMID 35301287, 2022). "The detection of EGFR ctDNA in the blood is crucial for the early detection of cancer." (PMID 35591635, 2022). "The first-generation, such as gefitinib and erlotinib usually with 4-anilinoquinazoline motifs, achieves initial good responses in the treatment of cancer patients with overexpression of EGFR but unfortunately, resistance to this class was acquired by most patients within 1 year." (PMID 36146940, 2022). "Our study revealed higher EGFR expression in a most metastatic HGSOC cases compared with their matched primary cancer deposits, which could have potential clinical significance." (PMID 35212471, 2022). "EGFR expression in HPV + cancer may be regulated by multiple factors, including existing complex mechanisms and HPV viral proteins." (PMID 35668455, 2022). "Only cancer cells harboring EGFR mutations display responsiveness to EGFR TKIs, and the remaining non-mutated cancer cells that are insensitive to the treatment generate primary drug resistance." (PMID 35408753, 2022). "Therefore, we conducted this investigation of ICI-based therapy versus classic chemotherapy for those that developed EGFR-TKI resistance from two cancer centers in China and to explore the optimal treatment modality." (PMID 36081560, 2022). "The data obtained suggest that boron clusters bind to the EGFR and have the potential to deliver the conjugated cargo (oligonucleotides or possibly other molecules, including anticancer drugs) to EGFR-overexpressing cancer cells via the EGFR-targeted pathway." (PMID 36499115, 2022). "Our observed results may also provide new insight into how sialylation affects EGFR dynamics and its role in cancer progression." (PMID 35955894, 2022). "One cancer had EGFR L858R, five had EGFR exon 19 deletion, and 14 were wild type for EGFR." (PMID 35202431, 2022). "The EGFR signaling pathway is one of the most dysregulated pathways in many human cancers." (PMID 36531494, 2022). "Similarly, in many cancers YAP/TAZ are overexpressed by upstream oncogenic signaling pathways such as EGFR, RAS-MAPK, PI3, WNT, and exhibit increased YAP nuclear localization." (PMID 36523977, 2022). "Moreover, some cancer-related pathways are also enriched in the C-score-identified buffering network, including the proto-oncogenes EGFR and MYC." (PMID 35194081, 2022).
cancer (continued). "This pan-cancer trial cohort includes patients with locally advanced or metastatic solid tumors with EGFR or HER2 exon 20 insertion mutations, in addition to allosteric HER2/HER3 mutations, HER2 amplification, or EGFR exon 19 deletion or L858R mutation." (PMID 34913823, 2022). "Some research has developed antibody fragments against EGFR for reducing cancer growth." (PMID 35578244, 2022). "EGFR plays a central role in the pathogenesis and progression of different carcinoma types." (PMID 35409325, 2022). "Heat map showed that compounds with high similarity to ACSL4 included inhibitor of Insulin Growth factor 1 receptor protein Tyrosine kinase, nalbuphine opioid receptor agonist, opioid receptor antagonist, EGFR inhibitor, Cytochrome P450 inhibitor and carcinoma cell growth inhibitor." (PMID 35126480, 2022). "Furthermore, elevated AnxA6 scaffold levels contributed to improving the efficacy of tyrosine kinase inhibitors (TKIs) targeting EGFR to reduce growth, migration, and invasive properties of EGFR overexpressing A431 carcinoma cells." (PMID 35806209, 2022). "We selected human epithelial SW620 carcinoma cells for their low level of native EGFR expression, for stable transfection with fluorescent protein labelled EGFR, and imaged these using single-molecule localization microscopy to quantify receptor architectures and dynamics upon EGF binding." (PMID 35612280, 2022). "Additionally, there seems to be a relation between Lng2 expression in carcinoma cells, EGFR signaling, and EMT." (PMID 36230826, 2022). "Finally, the well‐known carcinoma markers epidermal growth factor receptor (EGFR) and human epidermal growth factor receptor 2 (Her‐2) have also been exploited for targeting CD47 therapy." (PMID 35908284, 2022). "Such an increased on-rate could conceivably contribute to a depleted monomeric population, which has implications for carcinomas in which the expression level of EGFR is known to be high." (PMID 35612280, 2022). "Current potential lead compounds identification based on the in silico and in-vitro studies for EGFR overexpressed carcinoma that may have more robust pharmacological effects than currently available marketed drugs." (PMID 36457709, 2022). "In regards to EGFR, several inhibitors and monoclonal antibodies have already been therapeutically approved to target this protein due to its roles as an important driver of tumorigenesis in many cancer types." (PMID 34301218, 2021). "EGFR endocytosis is a novel therapeutic target in cancer with wild-type EGFR." (PMID 34884765, 2021). "Furthermore, the cytotoxic effect of 188Re-liposome-Fcy-hEGF/5-FC was evaluated in EGFR-overexpressing cancer cells compared with the treatment of liposome-Fcy-hEGF/5-FC or 188Re-liposome-Fcy-hEGF alone." (PMID 33672989, 2021). "Whether the relationship between JMJD8 and EGFR is direct or indirect and how JMJD8 regulates EGFR degradation in cancer cells remains unknown." (PMID 33442397, 2021). "In the long term, NiBh could be employed against other EGFR-expressing cancers and with a potential use in other species as well." (PMID 36405501, 2021). "Some antibodies are restricted to specific cancer types (e.g., EGFR‐, HER2‐expressing tumors) or could suffer from low selectivity because their target cell‐surface markers are also expressed by other cells (e.g., VCAM‐1, ICAM‐1)." (PMID 33448107, 2021). "A previous study suggested the involvement of EGFR in the pathogenesis and progression of cancers." (PMID 34367282, 2021). "Furthermore, our data strongly suggest that cancer patients receiving EGFR therapy should be screened for p120ctn protein expression in their tumors to assess the potential efficacy of the targeted therapy." (PMID 34784403, 2021).
cancer (continued). "Although it is now given as first-line therapy for EGFR mutant NSCLC, patients inevitably develop resistance through single amino acid substitutions at the EGFR cysteine residue C797 as well as other mechanisms that bypass dependence of the cancer cells on EGFR signaling for survival." (PMID 34944063, 2021). "However, the molecular mechanism of autophagy regulation by EGFR remains poorly understood in cancers, especially in OSCC." (PMID 34830108, 2021). "Indeed, uPAR and EGFR are to date a well-known couple, able to regulate cancer cell proliferation, adhesion and migration." (PMID 34055629, 2021). "In addition, preclinical studies have focused on exploring the benefit of epidermal growth factor receptor (EGFR) inhibitors such as gefitinib in EGFR-positive cancers." (PMID 33718194, 2021). "Mutations in the WNT (e.g. APC or CTNNB), EGFR (e.g. KRAS, PIK3C or BRAF) and TGF-β (e.g. SMAD4) signalling pathways gradually render cells independent from niche signals to grow autonomously and promoting cancer." (PMID 33594337, 2021). "They discovered a drug-induced increase in the stability of EGFR homodimers, which could have a biological impact on the proliferation potential of cancer cells." (PMID 34830837, 2021). "This work described a novel facile AffiBeads platform for the rapid and sensitive detection of low concentrations of cancer-derived EGFR-positive exosomes and could expand to any biomarker of interest." (PMID 34769444, 2021). "In the present study, EGFR expression was confirmed in all types of the MPM cancer cell lines." (PMID 34025789, 2021). "For instance, a mutated PA83 variant unable to bind to its native receptors due to mutations in the receptor-binding domain (termed mPA83), was fused to EGF (epidermal growth factor) and thus redirected to EGF receptors (EGFR), which are highly expressed in many cancer cells." (PMID 34733166, 2021). "EGFR is the third ranked putative target and is frequently upregulated in certain cancers." (PMID 33941241, 2021). "The findings of this study indicated that miR‐1169 and miR‐260 exosomal miRNAs may be specific characteristics to distinguish NSCLC patients with wild‐type EGFR and mutant EGFR in the early cancer stages." (PMID 33682961, 2021). "Furthermore, exosomal EGFR expression levels were found to be elevated in five out of nine cancer cases compared to healthy controls." (PMID 34830787, 2021). "Furthermore, it has been described that, in other types of cancer in which anti-EGFR treatment is Food and Drug Administration-approved, it is quite common for patients to develop resistance mechanisms towards EGFR-targeted therapy." (PMID 33886813, 2021). "Moreover, the cross-talk between PAKs and other oncogenic/pathogenic signaling pathways, such as CDKs/PAKs, EGFR/PAKs, and BRD4/PAKs, is very important in cancer progression and drug resistance." (PMID 33796531, 2021). "Furthermore, ERK signaling has been revealed to be modulated by the transactivation between PAR2 and EGFR in cancer cells." (PMID 33967759, 2021). "Next, we tested N1mAbs for the combinatorial effect with EGFR inhibitor because previous reports showed that EGFR is expressed in NB and adult cancers and could be a therapeutic target for these tumors." (PMID 34277416, 2021). "However, overall, this was insignificant compared with EGFR-positive cancer cell lines, with a median of zero and four AuNRs aggregates per cell for untargeted and targeted groups, respectively." (PMID 34683944, 2021). "RON expression combined with EGFR correlates with poorer outcomes for cancer patients." (PMID 34821550, 2021). "Moreover, molecular alterations of EGFR include overexpression, deletion, or amplification, in different types of cancer." (PMID 33435537, 2021). "In particular, some studies have shown that overexpression of the EGFR or its ligands may induce different types of cancer." (PMID 34126069, 2021).